CCR2 (C-C motif chemokine receptor 2)
Diseases named in the same sentence as CCR2 in open-access papers (continued):
Sharing a sentence is not in itself a finding about the gene and the disease.
atherosclerosis (continued). "In parallel, LPS directly increases lipid deposition in primary human adventitial fibroblasts, inducing secretion of molecules with prominent roles in atherosclerosis such as monocyte chemoattractant protein 1 (MCP-1), the main ligand for CCR2." (PMID 34439835, 2021). "Monocyte migration and adhesion to endothelial cells are crucial steps in the early stages of atherosclerosis development, in which ligand-receptor pairs such as MCP-1/CCR2, ICAM-1/Integrin αMβ2, and E-selectin/Integrin αMβ2 are crucially involved." (PMID 32793587, 2020). "When conjugated with gadolinium or europium cryptates, CCTV enabled targeted imaging (via magnetic resonance imaging and time-resolved fluorescence) of atherosclerosis, a chronic inflammatory condition in which the CCL2/CCR2 axis is highly dysfunctional." (PMID 31723548, 2019). "This suggests that Ly6Chigh monocyte recruitment, mediated by CCR2 and CCL2, to the plaque is essential for atherosclerosis progression." (PMID 29868610, 2018). "CC Chemokine Receptor 2 (CCR2) and its endogenous ligand CCL2 are involved in a number of diseases, including atherosclerosis." (PMID 28246398, 2017). "The knockout and transgenic studies provide convincing proof that individual chemokine-chemokine receptor signalling pathways are important in atherosclerosis, particularly the CCL2/CCR2, CCL5/CCR5 and CX3CL1/CX3CR1 pathways." (PMID 28282403, 2017). "The logistic regression, however, demonstrated a significant role for CCR5 expression as a predictor of atherosclerosis progression (B = 2.1, OR = 8.1, p = 0.04) and a negligible effect for CXC3R1 and CCR2 expression." (PMID 23659629, 2013). "The significance of chemokines (CCL2 [monocyte chemotactic protein-1], CCL5 [RANTES] and CX3CL1 [fractalkine]) and their receptors (CCR2, CCR5 and CX3CR1) in atherosclerosis has been demonstrated in animal models and clinical studies." (PMID 22815945, 2012). "The chemokine receptors CCR2 and CXCR2 were expressed in the arterial endothelial cells of human atherosclerosis, in addition to their expected expression in the U937 cells, which we have confirmed." (PMID 18579408, 2008). "Thus, by improving our understanding of the regulatory mechanisms that govern CCR2 expression on monocyte lineage cells, we can better appreciate how monocyte recruitment and activation is controlled during chronic inflammatory pathologies such as atherosclerosis." (PMID 16259633, 2005). "In addition to 18F-FDG and 18F-NaF, newer PET tracers are under investigation for better imaging atherosclerosis, such as CXCR4-targeted 68 Ga-pentixafor, CCR2-targeted 64Cu-DOTA-ECL1i, and CCR5-targeted 64Cu-DOTA-DAPTA." (PMID 40289041, 2025). "The lack of MCP-1, MCP-1 receptor CCR2 inhibition, IL-1β deficiency, and TNF-α inhibition have been shown to decrease atherosclerosis formation." (PMID 37107335, 2023). "CCR2 is highly expressed by monocytes and binds to CCL2 which is primarily secreted by monocytes, macrophages and dendritic cells, supporting a primary role for monocyte/macrophage activation in atherosclerosis." (PMID 37927302, 2023). "CCR2 has been reported to be involved in Treg cell recruitment, but this role has not been shown in atherosclerosis." (PMID 36077273, 2022). "E.g., it has been shown in atherosclerosis that the expression and function of chemokine receptors such as Ccr2, Ccr5 and Cx3cr1 differs between classical and non-classical monocytes." (PMID 36741412, 2022). "CCR2 expression also elicits the adhesion of classical and nonclassical monocytes to the vascular endothelium during atherosclerosis." (PMID 36286282, 2022). "Though both preclinical studies and clinical trials show the beneficial effects of CCR2 inhibition, especially in atherosclerosis, no drugs have been approved as yet." (PMID 36109744, 2022).
atherosclerosis (continued). "The first molecule that has been investigated in atherosclerosis pathogenesis is chemokine ligand 2 (CCL2), also known as monocyte chemoattractant protein-1 (MCP-1), and it works with receptor chemokine receptor type 2 (CCR2)." (PMID 34345249, 2021). "Monocyte subsets also differentially express the C-C chemokine receptor type 2 (CCR2) and the CX3C chemokine receptor 1 (CX3CR1), each of which are chemokine receptors with prominent functions in cell migration and endothelial adhesion during atherosclerosis." (PMID 34439835, 2021). "Future studies should clarify whether CCR1 and CCR2, in addition to CCR5, could contribute to the beneficial effects of direct CCL4 inhibition on atherosclerosis." (PMID 32911750, 2020). "Importantly, the authors found that timed pharmacological CCR2 neutralization caused inhibition of atherosclerosis without disturbing microvascular recruitment, providing a proof-of-principle treatment schedule for chrono-pharmacological intervention in atherosclerosis." (PMID 31847894, 2019). "Whereas in atherosclerosis models a reduction of atherosclerosis could be observed due to the specific function of RP105 on B cells and inhibition of CCR2 dependent macrophage migration." (PMID 29417051, 2018). "In the case of native atherosclerosis, recruitment of inflammatory Ly-6Chi monocytes into the atherosclerotic plaques requires particular chemokine–chemokine receptor interactions, involving CXCR1 in addition to CCR2 and CCR5." (PMID 22704806, 2012). "The chemokine receptors CCR2 and CX3CR1 are critical for the recruitment of “inflammatory” and “resident” monocytes, respectively, subpopulations that differentially affect vascular remodeling in atherosclerosis." (PMID 23029475, 2012). "Using MCP1/Ccl2 receptor-deficient mice to examine atherosclerosis, it was demonstrated that, in the absence of the receptor for MCP1/Ccl2, CCR2, there was a substantial reduction in arterial lipid deposition and diminished numbers of macrophages in the arterial wall." (PMID 40753563, 2025). "Accordingly, the critical role of CCR2/CCL2 in various inflammatory pathogeneses, including rheumatoid arthritis, asthma, multiple sclerosis, neuropathic pain, or atherosclerosis, has been largely documented and demonstrated in mice that are deficient for CCL2 or CCR2." (PMID 36729317, 2023). "A 7-d-amino acid peptidic CCR2 inhibitor called extracellular loop 1 inverso (ECL1i), d(LGTFLKC) has been identified and labeled to obtain a new probe for positron emission tomography in pulmonary fibrosis, heart injury, abdominal aortic aneurysm inflammation, atherosclerosis, head and neck cancer." (PMID 36729317, 2023). "In the Treg context, CCR2, CCR4 and CCR6 have previously been shown to be up‐regulated in Tregs migrating to non‐lymphoid tissues or sites of inflammation, and this may be the primary basis of their increase in the atherosclerosis phenotype." (PMID 37927302, 2023). "Furthermore, aspirin may normalize atherosclerosis and NAFLD by modulating the mannose receptor and CCR2 in macrophages." (PMID 32258142, 2020). "Absence of CCR2 in a mouse model of severe atherosclerosis reduced the formation of lesions." (PMID 31507616, 2019). "Some CXCR2- and CCR2-specific antagonists (i.e., reparixin and MLN1202) have already been tested as therapeutic drugs in clinical trials, like MLN1202, which is a CCR2-blocking monoclonal antibody shown to reduce high-sensitivity CRP as surrogate parameter for atherosclerosis." (PMID 22807925, 2012). "The absence of CCR2 on macrophages protects those mice from developing atherosclerosis." (PMID 20181074, 2010). "In mice lacking either MCP-1 or its receptor, CCR2 atherosclerosis is depressed." (PMID 18560564, 2008).
atherosclerosis (continued). "The role of MCP-1, a pro-inflammatory chemokine, in atherosclerosis was explored in ApoE−/− mice lacking CCR2, which reduced lesion formation without affecting plasma lipids, linking MCP-1 to atherosclerosis development." (PMID 40001895, 2025). "The absence of MCP-1 or its receptor CCR2 conversely results in a significant reduction in arterial lipid deposition, stressing MCP-1 as a driving force in the development of atherosclerosis." (PMID 39272977, 2024). "It is feasible that the increase in nonclassical monocytes expressing CCR2 may reflect an attempt of these immune cells to repair the injured vascular endothelium, a notion suggesting the use of these cells as an early marker of subclinical atherosclerosis in obese boys." (PMID 36286282, 2022). "We found that CCR2, but not CCR3 or CCR5, participated in HDL metabolism, thus representing a potential chemokine axis of atherosclerosis." (PMID 27458015, 2016). "Additionally, we observed a strong correlation of CCR2+ nonclassical monocytes with insulin resistance (r = 0.80, p < 0.01) in males with IMT ≥ p75 but not females with the same criterion for subclinical atherosclerosis." (PMID 36286282, 2022).
Obesity (121 papers, 2008 to 2026). Accumulation of substantial excess body fat. "CCR2 is a chemokine receptor that is closely associated with obesity-induced kidney injury and its associated oxidative stress and endoplasmic reticulum stress." (PMID 39334887, 2024). "Adipose tissue expression of CCL2 is increased in obesity, and we have shown that loss of CCR2 signaling reduces fibrocytes within the obese mammary gland." (PMID 38041006, 2023). "Herein, we conducted a pilot study to analyze CCR2+ monocyte subpopulations in children of both sexes with obesity, examining the association of these immune cells with cardiovascular risk factors, such as IMT and insulin resistance in a sex-dependent fashion." (PMID 36286282, 2022). "Circulating and AT levels of MCP-1 and levels of CCR2-expressing inflammatory cells are increased in obesity, and are strongly associated with IR." (PMID 31627295, 2019). "Accumulating evidence points to an important role of the MCP-1/CCR2 pathway in the development of obesity-associated inflammation in WAT and subsequent development of NASH." (PMID 28076416, 2017). "C-C chemokine receptor type 2 (CCR2)-deficient mice are protected against weight gain and display reduced development of obesity, illustrating the importance of this chemokine system." (PMID 27999564, 2016). "Studies in mice showed that CCR2 deficiency or antagonism of this receptor resulted in attenuation of systemic insulin resistance and development of obesity, hence suggesting a modulating role of CCR2 in this." (PMID 23379763, 2013). "In a mouse model of diet-induced obesity, CCR2 deficiency attenuated the development of obesity, adipose tissue macrophage accumulation, adipose tissue inflammation, and systemic insulin resistance." (PMID 20936118, 2010). "CCR2 influences the development of obesity and associated adipose tissue inflammation and systemic insulin resistance." (PMID 18570670, 2008). "However, blocking macrophage recruitment using CCR2-deficient mice attenuated obesity-induced miR-690 repression and APC loss in eWAT, leading to a higher number of small adipocytes." (PMID 40912400, 2025). "The inhibition of intestinal pro-inflammatory macrophage (M1-type-like) infiltration in genetically engineered animals (Ccr2 knockout mice and tamoxifen-inducible models) or by the oral administration of anti-inflammatory drugs mitigates obesity-associated inflammation and metabolic dysregulation." (PMID 40328980, 2025). "Inhibiting the MCP-1/CCR2 pathway has emerged as a potential strategy for alleviating insulin resistance and inflammation in adipose tissue, showing promise for treating metabolic disorders linked to obesity." (PMID 40699839, 2025). "However, CCR2+ monocytes/macrophages have also been reported to promote inflammation and obesity-associated metabolic dysfunction in various tissues." (PMID 38474365, 2024). "Therefore, enhancing surveillance of metabolic overload by CCR2-CX3CR1high monocytes seems a potent therapeutic approach to prevent obesity associated morbidities." (PMID 28993702, 2017). "Similarly, the inhibition of CCR2 also attenuates diet-induced insulin resistance and hepatic steatosis in obese mice, suggesting that MCP1/CCR2 could be a potential therapeutic target in obesity-associated metabolic complications." (PMID 35909571, 2022). "CC-chemokine receptor 2 (CCR2), a receptor for monocyte chemoattractant proteins (MCPs), plays a pivotal role in the entry of innate immune cells into tissue and influences systemic insulin resistance and adipose tissue inflammation associated with obesity in high-fat-fed murine models." (PMID 29967759, 2018). "Monocyte Chemoattractant Protein-1 (MCP-1) is central to inflammation triggered by obesity, acting by attracting monocytes to adipose tissue through its receptor, CCR2." (PMID 40699839, 2025).
Obesity (continued). "Obesity exacerbates this process by increasing adipocyte death, leading to the recruitment of chemokine C-C motif receptor 2 (CCR2)+ macrophages, which play a key role in liver injury and fibrosis in NASH." (PMID 40002806, 2025). "This highlights CCL2’s role in promoting inflammation through binding with CCR2 and cellular senescence, further exacerbating metabolic dysfunction in obesity." (PMID 39201480, 2024). "Knockdown of CCR2, even in the context of obesity, can attenuate renal injury, prevent excessive immune cell infiltration, and reduce inflammation and fibrosis, thus improving renal function." (PMID 39334887, 2024). "CCR2 is important in obesity, as CCR2-expressing monocytes are recruited to white adipose tissue, which leads to cytokine production and stimulation of adipogenesis, contributing to WAT deposition." (PMID 39457105, 2024). "Previous studies have reported CXCR2 and CCR2 as molecular players involved in the development of obesity-induced inflammation and insulin resistance." (PMID 38989000, 2024). "In summary, our study demonstrated that diet-induced obesity and pre-diabetes leads to the increased proliferation of pro-inflammatory CCR2+Ly6C+ monocytes/macrophages in skin wounds, contributing to their enhanced accumulation of in these wounds." (PMID 38474365, 2024). "Obese mice with the Ccr2−/− genotype show increased insulin sensitivity and greater glucose tolerance, which additionally indicates that CCR2 plays a role in regulating glucose levels in obesity." (PMID 39457105, 2024). "CCR2′s role in adipose tissue inflammation within the context of obesity and metabolic diseases further complicates our findings." (PMID 39199602, 2024). "In contrast, the deletion of CCL2 or its receptor (CCR2) in mice is followed by a significant reduction in the development of atherosclerotic plaques and obesity." (PMID 39275140, 2024). "Genetic deficiency of Ccr2 in mice fed a HFD reduced their food intake and decreased their development of obesity compared to wild-type mice." (PMID 37377968, 2023). "In obesity, macrophages accumulate within adipose tissue through resident proliferation and the recruitment of monocyte-derived precursors via the C-C motif chemokine receptor 2 (CCR2) pathway." (PMID 38062308, 2023). "In obesity and its related metabolic consequences, CCR2 plays a role in recruiting monocytes to tissues under metabolic stress, sustaining and amplifying inflammation in AT and the liver, and promoting insulin resistance." (PMID 37377968, 2023). "MCP-1 and CCR2 are secreted by adipocytes and other cells during obesity, which increases the infiltration of M1-polarized macrophages and stimulates the production of inflammatory cytokines." (PMID 37374121, 2023). "In conclusion, CCR2 expression in circulating monocyte subsets is associated with elevated IMT and insulin resistance in male children with obesity." (PMID 36286282, 2022). "In vivo studies in which CCR2 is genetically ablated or overexpressed show that these cells mediate obesity, obesity-induced hepatic steatosis, adipose tissue inflammation, insulin insensitivity, and the associated metabolic syndrome." (PMID 34613819, 2021). "Regarding the obesity status, independent associations were found only for TNF-α and CCR2 with SRA1 expression in NW (n = 12), and overweight (n = 32) participants." (PMID 34685582, 2021). "Currently, there is an increasing number of pre-clinical and clinical trials undergoing to evaluate the effects of antidiabetic and anti-obesity drugs, antibiotics, pan-caspase inhibitors, CCR2/5 antagonists, and others on NAFLD, NASH, and liver fibrosis." (PMID 34299189, 2021). "The rise in number macrophages in adipose tissue during obesity is not only due to the recruitment and differentiation of CCR2-dependent blood monocytes." (PMID 34613819, 2021). "In fact, many studies have shown the importance of MCP-1 and its receptor CCR2 on obesity-related metabolic disorders." (PMID 32437400, 2020).